CD47 (CD47 molecule)
Diseases named in the same sentence as CD47 in open-access papers (continued):
Sharing a sentence is not in itself a finding about the gene and the disease.
tumor (continued). "The encased doxorubicin can induce the immunogenic death of cancer cells and upregulate the expression of CD47 and calreticulin on the surface of cancer cells, while R837 can activate dendritic cells for enhanced processing and presentation of tumor antigens." (PMID 36341415, 2022). "Overall, inhibition of the CD47-SIRPα axis promotes tumor antigen cross-presentation to CD8+ T cells by dendritic cells, boosting the adaptive response." (PMID 35865547, 2022). "For example, activation of MYC can induce the transcription of both CD47 and PD-L1 and thereby suppress the anti-tumor immune response." (PMID 34980132, 2022). "HDAC6 is a tumor suppressor that inhibits Let-7i-5p to induce TSP1/CD47-mediated anti-tumorigenesis and phagocytosis of HCC." (PMID 35355509, 2022). "Anti-CD47-mediated phagocytosis of malignant cells by antigen-presenting cells (macrophages and dendritic cells) triggers an anti-tumor cytotoxic T-cell immune response." (PMID 35883692, 2022). "The mechanism of this strategy is to diminish the ‘don’t eat me’ signal of CD47-rich tumor cells with anti-CD47 antibodies while promoting ‘eat me signal’ with calreticulin." (PMID 35808648, 2022). "In pancreatic cancers, targeting CD47 efficiently enhanced the phagocytosis of tumor cells and the apoptosis of macrophages." (PMID 35585567, 2022). "Systemic suppression of CD47 expression enhances tumor ablation when combined with ionizing radiation, adoptive T cell transfer, chemotherapy, or a CTLA4 checkpoint inhibitor." (PMID 34841476, 2022). "For each type of cancer, MEC, AdCC, ACC, SDC, and AdCaNOS, we have examined the center of the tumor and the periphery of the tumor to understand which CD47+ cells dominate the tissue compartment." (PMID 36171566, 2022). "Since CD47 is commonly expressed at high levels in normal tissues, specific targeting of tumour cells via CD47 is questionable." (PMID 36310169, 2022). "These properties enable BsAbs to attach specifically to CD47+CD20+ tumor cells, resulting in phagocytosis." (PMID 35978372, 2022). "In vitro experiment and murine model proved that anti-CD47 induces the M1-polarization of macrophages that promotes an immune active tumor microenvironment." (PMID 35135556, 2022). "We designated this process as “ImmunoGenic Surrender” (IGS), whereby engagement of CXCR4 induces co-internalization and surface depletion of CD47 in tumor cells, followed by phagocytosis by macrophages." (PMID 36293358, 2022). "A recent study in a mouse model of breast cancer demonstrated that the simultaneous blockade of CD47 and PD-L1 inhibits tumor growth by enhancing T- and NK-cell activity." (PMID 35164813, 2022). "Phagocytosis by macrophages was greatly enhanced in miR-340-overexpressed tumor-bearing mice, and the overexpression of miR-340 further increased with CD47 blockade." (PMID 35464451, 2022). "Many studies have also indicated that macrophage deletion significantly inhibits CD47-mediated tumor remission and that anti-CD47 therapy depends on the presence of macrophages." (PMID 35317832, 2022). "Targeting the CD47-SIRPα axis combined with other therapeutic antibodies increased the anti-tumor efficacy of neutrophils." (PMID 35585567, 2022). "Ex vivo molecular imaging of 12 UTUC cases showed that fluorescent tracers based on anti-CD47 targeting guidance specifically bind to CD47 molecules on the surface of tumor cells." (PMID 35295998, 2022). "Interactions between CD47 on tumor cells and SIRPα on neutrophils inhibit neutrophil effector functions, allowing the tumor to escape immune surveillance." (PMID 35884427, 2022). "By combining a TAA-targeting mAb and anti-CD47 or anti-SIRPα mAb, immune cells can be recruited to the tumor and become fully activated by one antibody." (PMID 35884427, 2022). "In contrast, the combination treatment with irradiation and CD47 blockade significantly inhibited tumor growth." (PMID 36411318, 2022).
tumor (continued). "The results indicated that SIRPα-Exos presented higher CD47 affinity than control Exos, and enhanced tumor cell phagocytosis in vitro and in vivo." (PMID 36733388, 2022). "For example, CD47–signal regulatory protein α (SIRPα) axis has been proven critical for the tumor to escape from macrophage-mediated phagocytosis." (PMID 36497444, 2022). "As the natural defense of the immune system, the phagocytosis of macrophages is limited by CD47 anti-phagocytosis signal expressed on the surface of tumor cells." (PMID 35832081, 2022). "Inoculation of the CDDP and anti‐CD47 exosomes showed dramatically decreased tumor weight compared to the vehicle treatment and co‐administration groups." (PMID 36054073, 2022). "Here, knockdown of STAT3 altered calreticulin, ERp57, HSPs, and CD47 levels on the cell surface as well as the release of soluble mediators such as ATP, which stimulate the tumour antigen‐presentation ability of DCs and macrophages." (PMID 35665592, 2022). "Antibody-dependent cellular phagocytosis (ADCP) by macrophages, an important effector function of tumor targeting antibodies, is hampered by ‘Don ́t Eat Me!’ signals such as CD47 expressed by cancer cells." (PMID 36389667, 2022). "Inhibition of TNC reduced the phagocytosis of CD47-/- tumor cells in cocultures and enhanced the growth of CD47-/- xenografts in vivo." (PMID 35967394, 2022). "Overall, the doubling of CD47 KO metastases is suppressed ~4–5-fold by anti-Tyrp1 (Figure 2Biii), suggesting that anti-Tyrp1 drives tumor cell phagocytosis." (PMID 35454837, 2022). "This “decoy receptor” can bind CD47 on tumor cells, and can activate phagocytosis and Fc effector functions for maximum efficacy." (PMID 36293358, 2022). "Some CD47 antibodies have been reported to induce tumor cell death via a caspase-independent mechanism." (PMID 35865547, 2022). "A study indicated that the dual blockade of CD47 and PD-L1 overcomes innate and adaptive immune resistance to antibody immunotherapy and substantially enhances anti-tumor responses." (PMID 36009390, 2022). "Ligand-receptor interaction analyses indicated extensive cross-talk between the metastatic tumor cells and the MRC1+/CCL18+ macrophages; an example is the “don’t-eat-me” signaling between CD47 on tumor cells and SIRPA on the macrophages." (PMID 36376874, 2022). "SLAMF7 (signaling lymphocytic activation molecule family 7, also known as CRACC, CS1, and CD319) remarkably facilitates engulfment of a few hematopoietic tumor cells expressing SLAMF7 such as Raji during CD47-SIRPα blockade." (PMID 36081498, 2022). "Here, it transmits a “don’t eat me signal” upon binding to the phagocytosis checkpoint CD47 on tumor cells." (PMID 35883493, 2022). "This protein is expressed on phagocytic cells that interact with CD47-bearing EVs, inhibiting CD47 on cancer cells and thereby increasing cancer cell phagocytosis and inducing anti-tumour T cell responses." (PMID 36298556, 2022). "While tumor immunotherapy has been highly anticipated by researchers worldwide in recent decades, the discovery of tumor checkpoints in particular, including PD-L1, CTLA-4, CD47, and the Siglec family, is a landmark advance in tumor immunotherapy." (PMID 35733919, 2022). "CD47 blockade promotes phagocytosis of neoplastic cells by macrophages and tumor antigen-presentation by phagocytes to T cells." (PMID 35454825, 2022). "Meanwhile, the release of the anti-CD47 antibody enhanced the phagocytosis of macrophages to tumor cells and inhibited local tumor recurrence and potential metastasis and diffusion after surgery." (PMID 35892835, 2022). "Because the encapsulation of highly expressed CD47 biomimetic membrane, meTGCT exhibits superior immune escape ability as well as homologous targeting ability, which can be preferentially targeted to tumor sites and effectively enhanced tumor cell uptake." (PMID 36276645, 2022).
tumor (continued). "It was demonstrated that the CD47 mAb required macrophages, PBMCs, and possibly others for optimal tumor clearance, as validated by macrophage depletion using liposomal clodronate or NOD/SCID mice lacking human PBMCs." (PMID 35865547, 2022). "As an alternative to anti-CD47 antibodies, anti-SIRPα antibodies have also been studied for their ability to promote tumor elimination." (PMID 35884427, 2022). "Using xenotransplantation models, it has been shown that anti-CD47 antibodies inhibit tumor growth and metastasis." (PMID 36611344, 2022). "Accumulating data suggest that the CD47-SIRPα axis plays an important role in suppressing tumor phagocytosis by regulating the innate immune response." (PMID 35860564, 2022). "This idea is corroborated by the demonstration that CD47 blockade synergizes with PD-1/PDL-1 immune checkpoint inhibitors in immunocompetent mouse tumor models." (PMID 35538512, 2022). "Noteworthily, CD47 blockade in tumor cells can also enhance cross-presentation of tumor antigens for CD8+ T-cell activation, therefore improving anti-tumor effects." (PMID 35158779, 2022). "CD47 is an integrin also called the “don’t eat me” signal found on tumor cells, which inhibits their phagocytosis by macrophages after the binding of CD47 and SIRPα (signal-regulatory protein α) found on macrophages." (PMID 35214076, 2022). "Second, blood cells represent a large CD47-antigen sink which reduces drug availability for tumor cells and, thus, requires the administration of high maintenance doses to achieve saturation of CD47." (PMID 35538512, 2022). "We analyzed the relationship between CD47 expression and T stage, FIGO stage, and N status, as well as combined CD47 expression levels in patients with different tumor sizes but the same N status." (PMID 36611344, 2022). "Overexpression of CD47 has been reported to have critical implications in tumor cells evasion from macrophage-mediated phagocytosis." (PMID 35054787, 2022). "A reduction in the CD47/SIRPα signaling pathway via PD-1 blockade significantly reduced tumor growth by downregulating tumor immune-suppressive network mediators, such as MDSCs, tumor-associated macrophages, DCs, as well as effector T cells." (PMID 36233088, 2022). "Similar effects were observed in C57BL/6 mice treated with Panc02 (pancreatic cancer cell line), where CD47 mAb in combination with CTLA‐4 treatment inhibited tumour growth more profoundly than single treatment." (PMID 35908284, 2022). "Galectin-1 and galectin-3 make tumor cells prone to homologous aggregation, while CD47 allows tumor cells to escape phagocytosis by immune cells, thus improving tumor cell circulation in vivo." (PMID 36382024, 2022). "The inhibition of CD47-SIRPα axis in the tumor microenvironment facilitates the elimination of cancer cells mainly through the following four pathways." (PMID 35860564, 2022). "After CD47-SIRPα blockade, neutrophil-mediated tumor cell killing by trogoptosis is greatly promoted." (PMID 35884427, 2022). "In this study, we performed an IHC analysis of CD47 expression in both tumor cells and immune cells." (PMID 36171566, 2022). "Anti-CD47 antibodies have also been reported to strengthen the anti-tumor activity of macrophages, and some anti-CD47 mAbs in different tumors are in the clinical trials (NCT02953509, NCT04751383)." (PMID 36246629, 2022). "In the ROS-rich tumor microenvironment, it was found that the complex sustainably releases CD47 to activate the innate immune system, thereby recognizing cancer cells and promoting responsive growth of T cells." (PMID 35664731, 2022). "MSC‐derived exosomes express the tumor tropism of their maternal cells, as well as CD47, which reduces immune clearance and prolongs their in vivo circulation time." (PMID 35441482, 2022). "The upregulation of CD47 by tumor cells represents a defense mechanism against clearance by the immune system as it provides a “self” signal which allows the escape from immune cells elimination." (PMID 36297407, 2022).
tumor (continued). "In our study, we analyzed the association between CD47 expression and clinicopathological parameters and identified that high CD47 expression was associated with deeper level of invasion in BCC and larger tumor size in SCC." (PMID 36010209, 2022). "Some studies have examined the potential of CD47 as an anti-cancer therapeutic target to prevent immune evasion of tumor cells; however, the CD47-targeted therapies tested thus far have shown low efficacy and limited benefit." (PMID 35646646, 2022). "The relationship between increased CD47 expression and tumor cell invasiveness and metastasis has also been clarified in previous studies." (PMID 34189144, 2021). "In line with their findings, in this study, the expression of CD47 in PanNETs detected by IHC was conspicuously higher than that in adjacent non-tumor tissues." (PMID 33765961, 2021). "One of the major issues of CD47 as a target is its expression on physiological red blood cells, but off-tumor effect can be controlled with bi-specific Abs." (PMID 33800593, 2021). "The result showed that intestinal microbes outside the gastrointestinal tract are effective in promoting CD47 tumor immunotherapy." (PMID 34267748, 2021). "This enables selective blocking of CD47 in cancer cells and finally leads to immune cell activation and tumor cell eradication." (PMID 34729396, 2021). "Another strategy that we are pursuing is to knock down CD47 expression in the tumor microenvironment using antisense morpholino oligonucleotides, which limit both TSP1- and SIRPα-CD47 signaling." (PMID 33925464, 2021). "Priming of CD8+ T-cells can be further enhanced by antagonising tumour-induced suppression of phagocytosis with antibodies against CD47, facilitating antigen presentation by macrophages." (PMID 34452439, 2021). "CD47 is an immunoglobulin widely distributed on the surface of normal cells, which can negatively regulate anti-tumor immunity by inhibiting phagocytosis and participate in mediating cell proliferation, migration, apoptosis, and immune homeostasis." (PMID 34625124, 2021). "This study investigates the development of a SNALPs based system for co-delivery of ICD inducing drug (doxorubicin) and siRNA, to knockdown CD47, with the aim to synergistically improve tumor survival." (PMID 34522209, 2021). "Preclinical data on blockage of the CD47-SIRPα axis demonstrated enhanced phagocytosis of tumor cells in multiple types of cancer, which provides promising translational value for targeting interactions between TAMs and CSCs." (PMID 34831048, 2021). "The CD47 overexpressed on the surface of tumor cells can limit the ability of macrophages to engulf tumor cells by interacting with signal regulatory protein α (SIRPα) on macrophages; SIRPα acts as a “don’t eat me” signal." (PMID 34852849, 2021). "CD47 demonstrates its functions via SIRPα to inhibit macrophage phagocytosis, help tumor cells escape immune surveillance, and inhibit the elicitation of both the innate and adaptive immune responses." (PMID 34367975, 2021). "Preclinical studies have demonstrated that IBI322 can effectively block CD47/SIRP-α interaction and induce macrophages to phagocytose CD47-expressed tumor cells, which is equivalent to anti-CD47 monoclonal antibody." (PMID 34305918, 2021). "The results indicated that RS17 significantly promotes the phagocytosis of tumor cells by macrophages and had a similar therapeutic effect compared with a positive control (CD47 monoclonal antibodies)." (PMID 33629544, 2021). "ChIP-Seq traces generated from the ENCODE database showed a large accumulation of H3K4me2 in the CD47/CD274 promoter regions of many tumor cells." (PMID 33731702, 2021). "At the end of the experiment, the tumor weights and volumes in mice treated with FF or FF combined with anti-CD47 were lower than those in the control mice." (PMID 33937269, 2021).
tumor (continued). "We found that CD47 expression in the tumor microenvironment also regulates NK cell recruitment and transcriptional responses to activating stimuli, and its absence results in a defect in mitochondrial metabolism." (PMID 33925464, 2021). "Overriding CD47 while supplementing with FDA-approved IFNα that stimulates cytotoxic cells unleashes tumor clearance." (PMID 34885092, 2021). "In this study, it reports that CD47 blockade leads to inhibition of degradation of tumor mtDNA by activation of NADPH oxidase NOX2 in DCs, consequently, activates the mtDNA-cGAS-STING-IFN-γ pathway in DCs." (PMID 34512146, 2021). "In dedifferentiated liposarcoma, pleomorphic liposarcoma and epithelioid sarcoma, more than 90% of the tumor cells within the sample express CD47 in 71%, 64% and 63% of the samples, respectively." (PMID 34207243, 2021). "CD47 is expressed on tumor cell surface, on a bimodal way (either on 0% or >90% of tumor cells), protecting them from phagocytosis by an interaction with SIRPα on macrophage/dendritic cell surface." (PMID 34925348, 2021). "CD47 also mediates inhibitory thrombospondin-1 signaling in vascular cells, T cells and NK cells; blocking inhibitory CD47 signaling on cytotoxic T cells directly increases tumor cell killing." (PMID 34717705, 2021). "The combination of fenofibrate and anti-CD47 therapy significantly inhibited tumor growth in a 4T1 tumor-bearing mouse model." (PMID 33937269, 2021). "This is important as the adaptive immune system, especially CD8+ cytotoxic T cells, is also involved in tumor eradication after CD47 blockage." (PMID 34729396, 2021). "Anti-CD47 antibodies have been shown to stimulate macrophage tumour cell phagocytosis as well as antigen-specific CD8+ T-cell cytotoxicity, highlighting a potential synergy with ICB." (PMID 34944851, 2021). "Meanwhile, MYC-driven up-regulation of CD47, an antiphagocytic protein inhibiting the phagocytic effects of macrophages and DCs on tumor cells, on tumor cells can ultimately impair the potential of APCs to prime effector T cells." (PMID 34138315, 2021). "Previous literature found the success in the use of animal and humanized antibodies for blocking the CD47 pathway, resulting in the suppression and block of tumor growth." (PMID 34189144, 2021). "Immunotherapies blocking the CD47-SIRPα pathway can be achieved with antagonist molecules binding to SIRPα on macrophages or to CD47 on tumor cells." (PMID 34572013, 2021). "Interaction of SPP1 and its receptor CD47 further inhibits angiogenesis by antagonizing nitric oxide signaling in endothelial and vascular smooth muscle cells which, in turn, affects the tumor microenvironment." (PMID 33345281, 2021). "CD47 molecules expressed on tumor cells interact with signal-regulatory protein alpha (SIRPα) on TAMs to prevent phagocytosis, enabling the escape of innate immune surveillance." (PMID 33919979, 2021). "Within tumor cells, HIF-1α pathway activation aids tumor survival and combats the anti-tumor immune response by upregulating tumor expression of PD-L1 and CD47." (PMID 34868044, 2021). "This suggests that NTP treatment of the tumor can reduce the ability of CD47 to bind to SIRPα on innate immune cells." (PMID 33540720, 2021). "CaCO3 NPs loaded with the anti-CD47 antibodies (aCD47@CaCO3) were dispersed in the fibrinogen solution, and formed fibrin gel at the tumor surgical site through the interaction between fibrinogen and thrombin." (PMID 34823541, 2021). "Elimination of CD47 on tumor cells enhances the development of anti-tumor immune responses in preclinical models via dendritic cell-dependent mechanisms." (PMID 33816320, 2021). "Exosome-signal regulatory protein α (SIRPα) can interact with cluster of differentiation 47 (CD47) exiting in the tumor cells surface, thus restricting macrophages from engulfing tumor cells." (PMID 35047512, 2021).